ESM1 (endothelial cell specific molecule 1)
Diseases named in the same sentence as ESM1 in open-access papers (continued):
Sharing a sentence is not in itself a finding about the gene and the disease.
pericarditis (1 paper, 2020). An inflammatory process affecting the pericardium. "We therefore explored phenotypic associations at the identified cis-mQTL influencing multiple CpGs at the ESM1 DMR and found suggestive associations with pericarditis and kidney function." (PMID 32889533, 2020).
periodontal disease (1 paper, 2025). "Although elevated ESM-1 levels have been observed in various systemic inflammatory diseases, its role in periodontal disease, particularly in relation to established markers like TNF-α and VEGF-A, remains insufficiently explored." (PMID 40426985, 2025). "This study assessed the levels of ESM-1, VEGF-A, and TNF-α in GCF in the context of periodontal disease prior to and following NSPT." (PMID 40426985, 2025). "The correlations between GCF VEGF-A, ESM-1, and TNF-α levels and periodontal disease were also assessed." (PMID 40426985, 2025).
periodontitis (1 paper, 2025). An acute or chronic inflammatory process that affects the tissues that surround and support the teeth. "Ultimately, these findings suggest that reduced levels of TNF-α and ESM-1 in periodontitis patients following NSPT may be associated with ESM-1 and periodontal inflammation." (PMID 40426985, 2025).
pneumonia (1 paper, 2023). An acute, acute and chronic, or chronic inflammation focally or diffusely affecting the lung parenchyma, caused by an infection in one or both of the lungs (by bacteria, viruses, fungi, or mycoplasma.). "ESM1 is verified to be highly expressed in partial renal diseases, vascular inflammation, pneumonia and multiple tumors, and its crucial role in angiogenesis and tumor progression has also been confirmed." (PMID 37100467, 2023).
prostate tumor (1 paper, 2024). "Interestingly, ESM1 and CDT1 have been previously associated with prostate tumor progression." (PMID 38597610, 2024).
pulmonary-renal syndrome (1 paper, 2017). "This strategy is particularly appealing for the pulmonary-renal syndrome of anti-GBM disease as Esm-1 is primarily expressed in kidney but also lung." (PMID 28934365, 2017).
renal fibrosis (1 paper, 2020). A final common manifestation of a wide variety of chronic kidney diseases characterized by glomerulosclerosis and tubulointerstitial fibrosis. "This study proposes the overexpression of ESM1 promotes cell migration and renal fibrosis progression by regulating the EndoMT pathways in vitro and in vivo." (PMID 32781625, 2020). "This study presents the first evidence to suggest that elevated ESM1 expression promotes renal fibrosis by inducing the EndoMT." (PMID 32781625, 2020). "Further investigation is required to elucidate the molecular mechanism by which ESM1 promotes the EndoMT and cell migration and its contribution to the progression of renal fibrosis." (PMID 32781625, 2020). "Previous studies have suggested that ESM1 is secreted by vascular endothelial cells in several organs, but no direct evidence has shown that ESM1 is involved in the molecular mechanism underlying renal fibrosis." (PMID 32781625, 2020). "The current study investigates the role of ESM1 in renal fibrosis in vivo and in vitro." (PMID 32781625, 2020). "It is noteworthy that ESM1 may be a molecular target of renal fibrosis, and some clinical trials are proving that antifibrotic therapies are obviously worth clinical application in the future." (PMID 32781625, 2020). "This study investigates the role of ESM1 in renal fibrosis, using an in vivo unilateral ureteral obstruction (UUO) mouse model of renal fibrosis and in vitro mouse kidney MES 13 cells overexpressing ESM1." (PMID 32781625, 2020).
thyroid cancer (1 paper, 2024). "The profound impact of ESM1 knockdown on cellular mechanisms not only bolsters its position as a viable prognostic biomarker but also as a potential therapeutic agent in thyroid cancer." (PMID 38626010, 2024). "The scratch assay was used to detect the effects of knockdown of ESM1 expression on the migratory ability of thyroid cancer cells." (PMID 38626010, 2024). "By applying RNA interference techniques, specifically shRNA, we have elucidated the functional role of ESM1 in thyroid cancer." (PMID 38626010, 2024). "The current study seeks to fill this void in the literature by utilizing shRNA to knock down ESM1 in thyroid cancer cell lines and conducting a comprehensive analysis of its role." (PMID 38626010, 2024). "Flow cytometry was used to identify the effects of knockdown of ESM1 expression on apoptosis and the cell cycle distribution of thyroid cancer cells." (PMID 38626010, 2024). "The MTT assay was utilized to detect the effects of knockdown of ESM1 expression on the proliferative ability of thyroid cancer cells." (PMID 38626010, 2024). "Concomitantly, the transwell assay was utilized to detect the effect of knockdown of ESM1 expression on the invasive and metastatic ability of thyroid cancer cells." (PMID 38626010, 2024). "However, the literature on ESM1’s impact on thyroid cancer remains sparse, leaving its potential as a prognostic marker and therapeutic target largely untapped." (PMID 38626010, 2024). "Secondly, this investigation was conducted in vitro, and while it demonstrated that ESM1 inhibition could attenuate the proliferation and migration of thyroid cancer cells, the clinical relevance of these findings remains to be established." (PMID 38626010, 2024). "However, the precise relationship between ESM1 and the proliferation and migration of thyroid cancer cells, particularly in PTC, has been insufficiently explored." (PMID 38626010, 2024). "In light of our findings, ESM1 appears to be a key regulator of thyroid cancer cell biology and could be an invaluable addition to the therapeutic arsenal against PTC, potentially improving patient outcomes and quality of life." (PMID 38626010, 2024). "Furthermore, the knockdown of ESM1 effectively impedes the growth, migration, and invasion of thyroid cancer cells, indicative of the therapeutic potential observed in other forms of cancer." (PMID 38626010, 2024). "Our aim is to provide a nuanced understanding of ESM1’s involvement in thyroid cancer, which may facilitate its use as a significant biomarker for the disease." (PMID 38626010, 2024). "Furthermore, the biomarker potential of ESM1 in thyroid cancer diagnosis and prognosis has become increasingly apparent." (PMID 38626010, 2024). "Our study propels ESM1 to the forefront of the discussion on thyroid cancer treatment, suggesting that monitoring ESM1 expression could serve not only as a means of gauging disease progression but also as a guide for customizing patient-specific treatment plans." (PMID 38626010, 2024). "The observed effects on cancer cell viability, migration, and morphological integrity following ESM1 knockdown align with the therapeutic goals pursued in other cancer types, marking a milestone in the journey towards targeted treatment strategies for thyroid cancer." (PMID 38626010, 2024). "Our study aims to fill this research void by revealing that ESM1 levels are significantly higher in thyroid cancer tissues, including PTC, compared to adjacent non-tumorous tissues." (PMID 38626010, 2024).
thyroid tumor (1 paper, 2024). A benign or malignant neoplasm affecting the thyroid gland. "Next, we will conduct a critical experimental study on the mechanism of the inhibitory and apoptotic effects of ESM1 on thyroid tumors in detail based on the important data and findings of this paper, which will be presented in a separate article." (PMID 38626010, 2024).
venous thromboembolism (1 paper, 2026). Occlusion of the lumen of a vein by a thrombus that has migrated from a distal site via the blood stream. "Endothelial cell-specific molecule-1 (ESM1), a proteoglycan secreted by endothelial cells, is elevated in patients with venous thromboembolism (VTE), yet its role in coagulation regulation remains undefined." (PMID 41517829, 2026).
Venous thrombosis (1 paper, 2026). Formation of a blood clot (thrombus) inside a vein, causing the obstruction of blood flow. "Loss of esm1 in zebrafish results in vascular occlusion in the cardinal vein, whereas esm1 overexpression dose-dependently reduces venous thrombosis and prolongs TTO." (PMID 41517829, 2026).
viral infections (1 paper, 2020). "There is not any experimental evidence about the regulation of this gene in viral infections but it is shown that ALDH1A3 regulates 2 matricellular proteins (TNC1 and ESM1) in vascular smooth muscle cell proliferation." (PMID 32595353, 2020).
tumor (105 papers, 2009 to 2026). "ESM1 plays a pivotal role in the pathogenesis of several cancers, with its overexpression closely associated with tumor growth, progression, and angiogenesis." (PMID 40453069, 2025). "A dataset generated during our previous work allowed us to identify Endocan (ESM1 gene) as the most significantly upregulated secreted protein in tumor-associated VE cells when compared to the normal brain endothelium." (PMID 39773984, 2025). "GO analysis revealed the enrichment of pathways related to the extracellular matrix (ECM) and the regulation of epithelial cell migration and adhesion in ESM1+EC, which are associated with tumor development and metastasis." (PMID 38311726, 2024). "Elevated levels of ESM1 have been consistently linked to the altered immune environment of tumor vasculature and increased angiogenesis, essential to tumor growth and metastatic spread." (PMID 38626010, 2024). "Other studies have also suggested an association of ESM1 with tumor angiogenesis and immunological characteristics." (PMID 36518242, 2022). "Carcinogenesis of ESM-1 requires the existence of glycosylation chain and the integral protein structure, because specific protein mutations can lead to the loss of tumor promoting effect." (PMID 34109132, 2021). "Studies have shown that serum ESM1 levels are associated with survival time and tumor invasion in patients with cancer." (PMID 35047401, 2021). "It is worthy to note that ESM-1 is also a biomarker of neovascularization, the hallmark of tumor development, invasion, and metastasis." (PMID 34109132, 2021). "In this preliminary study, we found a significant positive association between tumor invasion and ESM-1 expression was observed only in vascular endothelial tissues, suggesting that tumor progression occurs mainly through ESM-1-associated mechanism in NCA." (PMID 31455321, 2019). "In NCA, a significant positive association between tumor invasion and ESM-1 expression was observed only in vascular endothelial tissues, suggesting that tumor progression occurs mainly through ESM-1-associated mechanism." (PMID 31455321, 2019). "Significant positive associations were noted between ESM-1 expression in vascular endothelial tissues and tumor invasion (P = 0.002) and tumor size (P = 0.020)." (PMID 31455321, 2019). "Significant positive associations were observed between ESM-1 expression in vascular endothelial tissues and tumor invasion (P = 0.002) and tumor size (P = 0.020)." (PMID 31455321, 2019). "In the most recent study, a significant positive association between tumour invasion and ESM-1 expression in null cell adenoma was reported." (PMID 31585531, 2019). "Inhibited expression of ESM1 in MOC2 was associated with much reduced tumor growth, compared to control cells." (PMID 27683113, 2016). "The EC biomarker ESM1, which is linked to a poor prognosis in human gastrointestinal and hepatocellular carcinomas, is also highly expressed in tumor ECs in a number of mouse tumor models." (PMID 37056346, 2023). "Our analysis showed that the tumour tissue had significantly higher ESM1 expression levels than normal ovarian tissue, which may be associated with abnormally elevated cell proliferation and tumour tissue revascularization." (PMID 37388244, 2023). "To determine whether ESM1 causes bevacizumab-resistant tumor metastasis, we overexpressed ESM1 in MDA-MB-231-S cells and named them MDA-MB-231-E (MDA-MB-231-S ovESM1)." (PMID 36428773, 2022). "ESM1 deletion caused significant necrosis in the tumor, which may have been due to the impaired nutritional transport function of microvessels." (PMID 36428773, 2022). "In addition, ESM1 overexpression was closely associated with tumor metastasis (P < 0.05) and lymphatic vascular invasion (P <0.05)." (PMID 36522312, 2022). "The overexpression of ESM1 might trigger accumulation of tumor mutation burden (TMB) during cell cycle of DNA replication in ACC." (PMID 34858850, 2021).
tumor (continued). "A variety of studies have reported that a high level of ESM-1 secretion is found in several cancers, including TNBC, and ESM-1 levels have been implicated to play a role in tumor metastasis, migration, and vascular invasion in human cancers by regulating the expression of MMPs." (PMID 34072157, 2021). "Moreover, ESM-1 overexpression in human embryonic kidney 293 cells causes tumor formation and growth in SCID mice." (PMID 32466580, 2020). "However, the invasiveness of tumor is certainly associated with the expression of ESM-1 via vascular structure." (PMID 31455321, 2019). "ESM-1 expression was reported to be associated with a larger preoperative tumor size." (PMID 31455321, 2019). "Moreover, the levels of mRNA of ESM1 were found to be highly regulated by inflammatory cytokines, such as tumor necrosis factor α and interleukin 1, and be linked with tumor growth and angiogenic process during tumor progression." (PMID 28108731, 2017). "In addition, the overexpression of ESM1 might trigger the accumulation of tumor mutation burden (TMB) during the cell cycle of DNA replication in ACC." (PMID 34858850, 2021). "However, we found that ESM-1 expression in only vascular endothelial tissues was associated with tumor invasion, suggesting that angiogenesis may be one of the mechanism underlying invasion in NCA, similar to other types of tumors." (PMID 31455321, 2019). "Xenograft tumor models were established using ESM1 whole-gene knockout mice, and Cluster of Differentiation 8 Positive (CD8+) T cell infiltration and apoptotic levels in tumors were detected via flow cytometry." (PMID 41930148, 2026). "ESM1 (endothelial cell-specific molecule 1) can promote cancer progression and metastasis through the regulation of tumor cell proliferation, migration, invasion and drug resistance." (PMID 40362181, 2025). "The addition of aPD-L1 enhances this effect, as evidenced by a further reduction in the proportions of myCAFs and ESM1+ ECs, thereby significantly limiting angiogenesis and affecting the oxygen supply to tumor cells." (PMID 40260248, 2025). "Notable examples within this intersecting group of genes included CDH3, ETV4, ESM1, and KRT80, all previously implicated in CRC progression and tumor microenvironment modulation." (PMID 40722723, 2025). "ESM1 promotes angiogenesis and tumor progression in CRC through activation of the PI3K/Akt/mTOR signaling pathway and upregulation of pro-angiogenic and inflammatory factors such as VEGF, COX-2, and HIF-1α." (PMID 40722723, 2025). "Broader oncology data reinforce ESM1 as a mediator in angiogenesis and tumour cell migration and further support its candidacy as a microenvironment-associated PG providing measurable readouts in clinical settings." (PMID 41463344, 2025). "The expression levels of ESM1 in PTC tissues form 53 tumor tissue samples and 59 matching adjacent normal tissue samples were detected by immunohistochemical analysis." (PMID 38626010, 2024). "Mice bearing NCI-N87/WT-ESM1 exhibited larger tumor nodules compared to those implanted with NCI-N87/Ctrl and NCI-N87/19del-ESM1." (PMID 39309430, 2024). "Upregulation of ESM1 in these cancers was shown to modulate different aspects of tumor progression, such as enhancing cell mobility, proliferation, stemness, and oncogenic pathway activation." (PMID 39309430, 2024). "The ability of silenced ESM1 to tumor formation in vivo was detected by tumor formation in nude mice." (PMID 38954708, 2024). "Analysis of a public microarray dataset (GSE27342), comprising 80 GC tumor tissues and their corresponding adjacent normal tissues, revealed significant upregulation of ESM1 in GC tissues." (PMID 39309430, 2024). "Thirdly, although the study highlights the involvement of ESM1 in the pathophysiology of PTC and delineates the downstream effects of ESM1 knockdown on tumor cell behavior, the intricate interactions between ESM1 and established oncogenic pathways in PTC." (PMID 38626010, 2024).